HDAC6 (histone deacetylase 6)
Diseases named in the same sentence as HDAC6 in open-access papers (continued):
Sharing a sentence is not in itself a finding about the gene and the disease.
Alzheimer disease (continued). "In any case, these data strongly support development of HDAC6 inhibitors, such as tubastatin, as possible treatments for Alzheimer’s disease and other tauopathies." (PMID 24576665, 2014). "It was reported recently that HDAC6 exhibits increased activity in cerebral cortex and hippocampus of Alzheimer's disease patients." (PMID 20520769, 2010). "Compared to the extensive biological evaluation of hydroxamate-based HDACi, there has been limited investigation into the pharmacokinetics (PK), pharmacodynamics (PD), and pharmacological effects of mercaptoacetamide-based HDAC6 inhibitors in cancer and Alzheimer’s disease models." (PMID 40284012, 2025). "Notably, genetic or pharmacologic inhibition of HDAC6 has been found to exert neuroprotective effects in ischemia stroke, Huntington's disease, Alzheimer's Disease, and hemorrhagic stroke." (PMID 37665135, 2024). "Thus, pharmacotherapy with HDAC6 inhibitors in animals simulating Alzheimer’s disease has demonstrated significant therapeutic potential due to the modulation of key links in the pathogenesis of this disease." (PMID 37298694, 2023). "Some studies reported decreased levels of acetylated tubulin in the postmortem brain of Alzheimer’s disease patients, which could be explained by the higher abundance of HDAC6 found in Alzheimer’s disease." (PMID 37106761, 2023). "Notably, recent studies have found that HDAC6 inhibition resulted in brain protection in several types of central nervous system disorders including Alzheimer’s disease, Huntington’s disease, and ischemia stroke." (PMID 37138816, 2023). "Previous studies have shown that inhibition of HDAC6 protects neurons in many neurological disorder models, including Alzheimer’s disease, Parkinson’s disease, Huntington’s disease, amyotrophic lateral sclerosis (ALS), Charcot-Marie-Tooth disease, and ischemic stroke." (PMID 35585040, 2022). "A number of animal studies have also pointed to a role for HDAC6 in Alzheimer’s disease." (PMID 30935091, 2019). "There is now an extensive body of evidence demonstrating that HDAC6 may play critical roles in different neurodegenerative diseases such as Huntington’s, Parkinson’s and Alzheimer’s disease." (PMID 30999900, 2019). "In addition to the anti-tumor activity, pharmacological inhibition or genetic ablation of HDAC6 have been shown to protect against cognitive deficits in rodent models of Alzheimer’s disease (AD)." (PMID 30270813, 2018). "Interestingly, inhibition of the deacetylating function of HDAC6 or increasing acetylation of α-tubulin have been shown to ameliorate axonal transport deficits in models for Parkinson’s disease and Alzheimer’s disease." (PMID 27957719, 2017). "One interesting observation is the finding that HDAC6 expression is increased by 52% in the Alzheimer’s disease cortex and by 91% in the Alzheimer’s disease hippocampus, when compared with young normal brains, as tau pathology progresses from entorhinal to hippocampal to neocortical regions." (PMID 24576665, 2014). "In addition to the polyglutamine diseases, over-expression of HDAC6 was protective in Drosophila melanogaster models of Parkinson's disease and Alzheimer's disease." (PMID 21677773, 2011). "Moreover, it is possible that, in Alzheimer's disease, aberrant HDAC6 levels are induced by increased activity of GSK3β." (PMID 20520769, 2010). "In particular, abnormal mitochondrial transport, which has been observed in such disorders as Alzheimer's disease and Parkinson's disease, could result from the misregulation of HDAC6 by GSK3β." (PMID 20520769, 2010). "For hydroxamic acids with high HDAC6-inhibiting activity, we also conducted docking analyses against the crystal structure of HDAC6 (PDB: 5EDU), where the features of the interaction of compounds with the sixth isoform of human HDAC, most commonly associated with Alzheimer’s disease, were revealed." (PMID 37298694, 2023).
Alzheimer disease (continued). "In search of novel multi-mechanistic approaches for treating Alzheimer’s disease (AD), we have embarked on synthesizing single small molecules for probing contributory roles of the following combined disease targets: sigma-1 (σ-1), class IIb histone deacetylase-6 (HDAC-6), and oxidative stress (OS)." (PMID 37894975, 2023). "A previous study has reported that the E3 ubiquitin ligase CHIP interacted with HDAC6 and promoted its poly-ubiquitination to suppress abnormal accumulation of the microtubule-binding protein tau, which was correlated with cognitive decline in Alzheimer's disease." (PMID 28599312, 2017). "Additionally, HDAC6 inhibition could also improve cognitive deficits in a mouse model for Alzheimer’s disease, has also been shown to exhibit antidepressant effects, and its therapeutic effect has also been demonstrated in a model of ischemic brain infarction." (PMID 27957719, 2017). "We report that mice lacking HDAC6 are cognitively normal but reducing endogenous HDAC6 levels restores learning and memory and α-tubulin acetylation in a mouse model for Alzheimer's disease (AD)." (PMID 23184605, 2013).
lung carcinoma (39 papers, 2015 to 2025). "A dual HDAC6/HSP90 inhibitor inhibited the cell growth of lung cancer cell lines in association with caspase-dependent apoptosis, further suppressing the growth in human H1975 xenograft tumors." (PMID 37628767, 2023). "In conclusion, High expression levels of HDAC6 and Pin1 were found to be associated with poor outcome in lung cancer." (PMID 33162791, 2020). "Recent studies suggest that EPAC1 can induce the migration of lung cancer cells by increasing the expression of histone deacetylase 6 (HDAC6), which in turn causes a decrease in α-tubulin acetylation and an increase in microtubule dynamics." (PMID 31775395, 2019). "Previous studies have shown that loss of HDAC6 downregulates EGFR expression in lung cancer cells." (PMID 29113288, 2017). "The role of HDAC6 in hepatocellular carcinoma is controversial, and its association with prognosis in lung cancer is still unknown." (PMID 26388610, 2015). "It inhibited HDAC6 activity, disrupting the HDAC6–Hsp90 interaction, which led to altered Hsp90 function and promoted its degradation in lung cancer cells." (PMID 41296425, 2025). "Of note, HDAC6 is a significant regulator of EGFR signalling activity, in which the knockout of HDAC6 in lung cancer cells caused premature EGFR degradation and trafficking." (PMID 39941046, 2025). "Upregulated EGFR activity is a major drug target for the treatment of solid tumours and the microtubule-dependent transport of EGFR endosomal vesicles by α-tubulin acetylation links HDAC6 to the pathogenesis of prostate, pancreatic, and lung cancer cells." (PMID 39941046, 2025). "In lung cancer, it has been reported that the high HDAC6 expression group exhibits a significantly poorer response to immunotherapy and significantly shorter progression-free survival compared to the low expression group." (PMID 39063958, 2024). "Herein, we reported that HDAC6 was upregulated in lung cancer and strongly correlated with poor prognosis." (PMID 36639650, 2023). "Similar to our findings, HDAC6 silencing enhanced tubulin acetylation and thus attenuated lung cancer growth, indicating that HDAC6 functions as a tumor promotor." (PMID 36639650, 2023). "We further investigated the role of HDAC6 in 3D tumor spheroid growth in patient-derived primary lung cancer." (PMID 36639650, 2023). "The present study revealed the biological role of HDAC6 in lung cancer cell growth and its molecular mechanism." (PMID 36639650, 2023). "Taken together, our results suggested that suppression of HDAC6 attenuated lung cancer growth via a GRP78-ERK-dependent mechanism." (PMID 36639650, 2023). "Mechanistically, HDAC6 inhibition was able to attenuate lung cancer growth by upregulating tubulin acetylation and downregulating p-ERK." (PMID 36639650, 2023). "Consistent with our study, HDAC6 was significantly elevated in lung cancer cells and malignant tissues, and HDAC6 inhibition was able to attenuate lung cancer cell growth, suggesting HDAC6 as a potential prognostic/therapeutic target in lung cancer." (PMID 36639650, 2023). "HDAC6 expression in clinical samples obtained from lung cancer tissues and patient-derived primary lung cancer cells was evaluated using qRT–PCR and Western blot analysis." (PMID 36639650, 2023). "For example, HDAC6 inhibitors can inhibit the immunosuppressive function of Treg cells in lung cancer." (PMID 36270986, 2022). "Scriptaid targets HDAC1, 2, and 8, and HDAC6 of Class IIb and has been developed as a potent HDACi with anti-tumour activity against several cancers such as endometrial, ovarian, colon or lung cancer." (PMID 35632748, 2022). "Several types of research and preclinical studies have revealed the significant role of HDAC6 inhibitors in the treatment of lung cancer." (PMID 36559012, 2022). "In another study, increased HDAC6 expression in lung cancer cell by Isoproterenol treatment led to inhibition of ERK signaling." (PMID 35159049, 2022).
lung carcinoma (continued). "It is worth noting that it is now widely accepted that pyruvate dehydrogenase kinase 3 (PDK3) and histone deacetylase 6 (HDAC6) inhibitors can be used to treat lung cancer." (PMID 36559012, 2022). "In vitro and in vivo studies show that the combination of resminostat (an HDAC-6 inhibitor) with docetaxel induces microtubule stabilization through the polymerization and acetylation of H3-histone into tubulin in lung cancer." (PMID 36263432, 2022). "Studies also show that EPAC signaling can help cancer cells move by increasing the expression of histone deacetylase 6 (HDAC6) or by making it easier for β-catenin to move into the nucleus and increase transcription in lung cancer cells." (PMID 35805104, 2022). "Recently, the role of HDAC6 in chemotherapy efficacy in several cancers, including lung cancer, has been explored by our group and others." (PMID 34746935, 2021). "Disruption of MMP‐9 protein stability via honokiol was through HDAC6 activity inhibition, and following the suppression lung cancer cell migration and invasion." (PMID 32180962, 2020). "Our data suggest that Pin1 acts as an important regulator to manage HDAC6 expression for cell motility in lung cancer cells." (PMID 33162791, 2020). "It is elusive that the higher expression levels of HDAC6 and Pin1 in the variety of lung cancer cell lines are coincident case or attribute to their biochemical or functional relevance." (PMID 33162791, 2020). "Intriguingly, higher expression levels of HDAC6 and Pin1 are coincidently present in a variety of lung cancer cells." (PMID 33162791, 2020). "Following, we attempt to understand what way the Pin1 sustain higher HDAC6 expression level in lung cancer cells." (PMID 33162791, 2020). "In the present study, we attempted to elucidate the relationship between HDAC6 and Pin1 in lung cancer." (PMID 33162791, 2020). "To advance the functional and biochemical relationship of HDAC6 and Pin1 in lung cancer, we firstly quantified the expressions of HDAC6 and Pin1 in a variety of non-small lung cancer cell lines." (PMID 33162791, 2020). "In our previous study, we have been characterized that HDAC6 is one of Pin1 substrates and the involvement of Pin1 in HDAC6-mediated cell motility concerns with tumor metastasis in lung cancer cells." (PMID 33162791, 2020). "Suppression of HDAC6 activity via honokiol leads to disrupting EGFR and Hsp90 association following by EGFR degradation in lung cancer." (PMID 32180962, 2020). "Meanwhile, honokiol‐suppressed MMP‐9 expression and invasion ability of H1299 lung cancer cells was rescued by HDAC6 overexpression." (PMID 32180962, 2020). "Generally, high expression level of HDAC6 is present in large cell and squamous cell carcinomas of non‐small cell lung cancer (NSCLC)." (PMID 33162791, 2020). "In parallel, the results from real-time PCR demonstrated that ectopic expression of ΔN-HDAC6-His decreased MMP2 mRNA expression levels, suggesting that nuclear HDAC6 is able to transcriptionally regulate MMP2 expression in lung cancer cells." (PMID 26388610, 2015). "In our study, ectopic expression of HDAC6 and ΔN-HDAC6-His, which restricted HDAC6 to the nucleus, enhanced the migration ability of lung cancer cells." (PMID 26388610, 2015). "In this study, we demonstrated the effects of semisynthesized NBM-T-BBX-OS01 (TBBX) from osthole on HDAC6-mediated growth arrest in lung cancer cells." (PMID 25946558, 2015). "In this study, we provided evidence demonstrating that increased nuclear translocation of HDAC6 prevented invasion by lung cancer cells." (PMID 26388610, 2015). "Our study demonstrated that an increase in the nuclear translocation of HDAC6 prevented the invasion of lung cancer cells." (PMID 26388610, 2015). "In addition, HK suppressed the migration and invasion of H1299 lung cancer cells by disrupting the expression of matrix metalloproteinase 9 (MMP9) through HDAC6 modulation." (PMID 41296425, 2025).
lung carcinoma (continued). "Moreover, Pin1 is an essential regulator in managing histone deacetylase 6 (HDAC6), influencing the motility of the cells in lung cancer." (PMID 39624096, 2024). "HDAC6 was upregulated in lung cancer specimens and significantly correlated with poor prognosis." (PMID 36639650, 2023). "In addition, suppression of HDAC6 strongly attenuated an in vitro 2D lung cancer cell growth and an in vitro 3D patient derived-lung cancer spheroid growth." (PMID 36639650, 2023). "HDAC6 promoted lung cancer proliferation, metastasis, and chemotherapy resistance." (PMID 36639650, 2023). "Since HDAC6 plays an important role in lung cancer pathogenesis, we further investigated whether suppression of HDAC6 by siHDAC6 impeded lung cancer growth via a GRP78-dependent mechanism." (PMID 36639650, 2023). "For example, quisinostat is an inhibitor of HDAC-6 in lung cancer." (PMID 36263432, 2022). "Accordingly, the results designated that the stimulation of MMP‐9 protein instability and degradation via honokiol was triggered by inhibiting the function of HDAC6‐mediated Hsp90 chaperone and followed by the suppression of lung cancer cell migration and invasion." (PMID 32180962, 2020). "Thus, this study suggested that anti-Pin1 is promising strategies to downregulate HDAC6 expression and can be considered an anti-metastasis in lung cancers." (PMID 33162791, 2020). "In addition, honokiol‐inhibited MMP‐9 expression was rescued in HDAC6‐overexpressed lung cancer cells." (PMID 32180962, 2020). "The regulation of Pin1 on HDAC6 expression improves cell motility in lung cancer cells." (PMID 33162791, 2020). "Disruption of MMP‐9 protein associated with Hsp90 and following by MMP‐9 degradation leading to the repression of migration and invasion activity via honokiol might result from HDAC6 inhibition in lung cancer cells." (PMID 32180962, 2020). "Furthermore, the invasion of honokiol‐repressed lung cancer cells was reverted by overexpressed‐HDAC6." (PMID 32180962, 2020). "Interestingly, the change in Pin1 expression levels in lung cancer cells line is similar to HDAC6 expression patterns in those cells lines." (PMID 33162791, 2020). "Moreover, review of high-density TMAs showed both USP10 and HDAC6 overexpression in ovarian and lung cancer patient samples and a positive correlation between their expression." (PMID 32382008, 2020). "In our in vitro study, we found that the ectopic expression of nuclear HDAC6 reduced the invasiveness of lung cancer cells, which may result from HDAC6-mediated deacetylation of NF-κB, which downregulated MMP2 expression." (PMID 26388610, 2015). "However, the relationship between cell cycle arrest and HDAC6 inhibition in lung cancer is still unclear." (PMID 25946558, 2015). "Our results indicate that the nuclear translocation of HDAC6 functionally inhibits the invasiveness of lung cancer cells that may occur through the inhibition of MMP2 expression." (PMID 26388610, 2015). "Thus, the development of novel small molecules targeting the upstream regulators, such as PKCε and cytoplasmic deacetylases that promote the nuclear translocation of HDAC6, may provide an opportunity to prevent the metastasis of lung cancer." (PMID 26388610, 2015). "Similar results were observed using two selective HDAC6 inhibitors, BML281 and WT161 in both A549 and PC9 lung cancer cells." (PMID 40091029, 2025). "Earlier DRUGSURV searches found that lung cancer patients with increased HDAC1, HDAC2, and HDAC6 had a poor prognosis." (PMID 40006525, 2025). "A recent study indicated that saturated fatty acids such as pentadecanoic acid and others inhibited HDAC6, resulting in the inhibition of MCF-7 breast and A549 lung cancer cells." (PMID 36979868, 2023). "Another compound, honokiol, derived from Magnolia officinalis, was found to inhibit migration and invasion in H1299 lung cancer cells by disrupting the expression of MMP‐9 and the Hsp90/MMP‐9 interactions mediated by HDAC6." (PMID 37697969, 2023).